RNU7-43P (RNA, U7 small nuclear 43 pseudogene)
Synonyms: U7.43; RNU7-118P
Gene: Small nuclear RNA gene on chromosome 17 (8,511,125 to 8,511,188, forward strand). Ensembl gene ENSG00000252363.
Homologues: Orthologues: macaque U7 (77% identical). Paralogues in human: RNU7-2P (86% identical), RNU7-8P (86% identical), RNU7-13P (84% identical), RNU7-18P (84% identical), RNU7-26P (84% identical), RNU7-11P (83% identical), RNU7-25P (83% identical), RNU7-40P (83% identical), RNU7-41P (83% identical), RNU7-48P (83% identical), U7 (83% identical), RNU7-1 (81% identical), and 143 more.